IGHD (immunoglobulin heavy constant delta)
Description:
Constant region of immunoglobulin heavy chains. Immunoglobulins, also known as antibodies, are membrane-bound or secreted glycoproteins produced by B lymphocytes. In the recognition phase of humoral immunity, the membrane-bound immunoglobulins serve as receptors which, upon binding of a specific antigen, trigger the clonal expansion and differentiation of B lymphocytes into immunoglobulins-secreting plasma cells. Secreted immunoglobulins mediate the effector phase of humoral immunity, which results in the elimination of bound antigens. The antigen binding site is formed by the variable domain of one heavy chain, together with that of its associated light chain. Thus, each immunoglobulin has two antigen binding sites with remarkable affinity for a particular antigen. The variable domains are assembled by a process called V-(D)-J rearrangement and can then be subjected to somatic hypermutations which, after exposure to antigen and selection, allow affinity maturation for a particular antigen. IgD is the major antigen receptor isotype on the surface of most peripheral B-cells, where it is coexpressed with IgM. The membrane-bound IgD (mIgD) induces the phosphorylation of CD79A and CD79B by the Src family of protein tyrosine kinases. Soluble IgD (sIgD) concentration in serum below those of IgG, IgA, and IgM but much higher than that of IgE. IgM and IgD molecules present on B cells have identical V regions and antigen-binding sites. After the antigen binds to the B-cell receptor, the secreted form sIgD is shut off. IgD is a potent inducer of TNF, IL1B, and IL1RN. IgD also induces release of IL6, IL10, and LIF from peripheral blood mononuclear cells. Monocytes seem to be the main producers of cytokines in vitro in the presence of IgD.
Synonyms: FLJ00382; FLJ46727; MGC29633
Gene: Immunoglobulin constant (C) gene on chromosome 14 (105,836,765 to 105,845,677, reverse strand). Ensembl gene ENSG00000211898.
Subcellular location: Secreted (Isoform 1); Cell membrane (Isoform 2)
Pathways (Reactome):
Immune System: Antigen activates B Cell Receptor (BCR) leading to generation of second messengers; CD22 mediated BCR regulation
Disease: Potential therapeutics for SARS
Homologues: Paralogues in human: IGHM (24% identical), IGHE (23% identical), IGHA1 (23% identical), IGHA2 (23% identical), IGHG3 (23% identical), IGHG1 (22% identical), IGHG4 (22% identical), IGHG2 (22% identical), IGLL1 (10% identical), IGLL5 (10% identical), IGHV3OR16-13 (8% identical), IGHV3-33 (8% identical), and 65 more.
Diseases named in the same sentence as IGHD in open-access papers:
IGHD is named in the same sentence as 25 diseases in open-access papers, as found by Europe PMC text mining. Sharing a sentence is not in itself a finding about the gene and the disease. The quoted sentences say what the papers report.
breast carcinoma (3 papers, 2019 to 2022). "The KM analysis, along with the typical IHC staining of SLIT3, TNN, IGHD, and KRRB1, showed that the expression was significantly different between normal and breast cancer tissues and confirmed the prognostic effect of the TME risk signature." (PMID 36059555, 2022). "In the breast cancer lymph node, most cells classified as naïve by gene expression had IGHM or both IGHM and IGHD antigen–receptor mRNA transcripts by nanopore sequencing while more than two-thirds of memory B cells expressed IGHA or IGHG." (PMID 31311926, 2019).
myeloma (2 papers, 2020 to 2026). "For each patient, the following category of MM was available: light chain only, IGHA+, IGHG+, or other (including IGHM+, IGHD+, and IGHE+ rare myelomas)." (PMID 41286079, 2026). "Overall, the gene repertoire in our series was very close to previous reports, although functional IGHV and IGHD genes, whose use has not been reported in myeloma to date, have been found in this cohort probably due to its larger size." (PMID 32029700, 2020).
periodontitis (2 papers, 2022 to 2024). An acute or chronic inflammatory process that affects the tissues that surround and support the teeth. "In this study, seven genes (CD19, CXCR4, FABP4, FOS, IGHD, IL2RG, and PPBP) were significantly up-regulated in periodontitis samples." (PMID 39917706, 2024). "A total of 7 genes (CD19, CXCR4, FABP4, FOS, IGHD, IL2RG, and PPBP) were upregulated in periodontitis samples." (PMID 39917706, 2024).
antibody deficiency (1 paper, 2024). "The comparison of IGHD, IGHM and IGHG(1 to 4) gene expression in PBMCs from TTD1 patients and healthy controls showed reduced gene expression of IGH chain genes in the patients thus indicating transcriptional impairment in B-cells likely to result in antibody deficiency." (PMID 39055713, 2024).
B cell lymphoma (1 paper, 2019). "Tumor-specific IGK locus gene rearrangements and their specific clonotypes could be detected in all 14 samples (100%) analyzed by NGS, while IGHV-IGHD-IGHJ and IGHD-IGHJ gene rearrangements were detected in 10 of 14 (71%), and 13 of 14 (93%) B cell lymphoma cases by NGS, respectively." (PMID 31197258, 2019).
Hodgkins lymphoma (1 paper, 2023). A heterogeneous group of malignant lymphoid neoplasms of B-cell origin characterized histologically by the presence of Hodgkin and Reed-Sternberg (HRS) cells in the vast majority of cases. "Being aware of this peculiar IgD expression pattern in naïve B cells, we detected a heterozygous IGHD nonsense variant (c.41_42insG; p.C15VfsX21) in exon 1 in a 22-year-old patient suffering from Hodgkin’s lymphoma during immunologic follow-up three years after completion of chemotherapy." (PMID 36776874, 2023).
Insulin resistance (1 paper, 2023). Increased resistance towards insulin, that is, diminished effectiveness of insulin in reducing blood glucose levels. "Besides recapturing known biomarkers for insulin resistance, we have been able to discover three novel proteins, to the best of our knowledge, associated with insulin resistance: IGHD, IGKC and PZP." (PMID 37903988, 2023).
leukemia (1 paper, 2016). A malignant (clonal) hematologic disorder, involving hematopoietic stem cells and characterized by the presence of primitive or atypical myeloid or lymphoid cells in the bone marrow and the blood. "These clones appear to be related by secondary rearrangement, with identical 84 bp region spanning the IgHD-IgHJ and 13 bp non-template region, suggesting clonal evolution of the leukemia." (PMID 27211266, 2016).
liver disease (1 paper, 2025). "IGHD, the delta heavy chain of immunoglobulin D (IgD), is expressed on B cells and involved in immune regulation, but its role in liver disease is largely unexplored." (PMID 41301514, 2025).
lymphoma (1 paper, 2019). A malignant (clonal) proliferation of B- lymphocytes or T- lymphocytes which involves the lymph nodes, bone marrow and/or extranodal sites. "Finally, the paired samples Diag4 and Relap4 displayed distinct IGHV-IGHD-IGHJ and IGHD-IGHJ gene rearrangements at diagnosis and relapse, while specific IGK locus rearrangements were only detected at diagnosis, suggesting that these lymphoma samples were most likely clonally distinct." (PMID 31197258, 2019).
osteosarcoma (1 paper, 2022). A usually aggressive malignant bone-forming mesenchymal neoplasm, predominantly affecting adolescents and young adults. "Naïve IGHD+ B and immune regulatory IGHA1+ B cells were largely identified in MPE, whereas bone metabolism‐related CLEC11A+ B cells were significantly enriched in osteosarcoma PT." (PMID 36305631, 2022).
steatosis (1 paper, 2025). Increased lipid within the cytoplasm of cells. "Specifically, H4C1, OIT3, ANPEP, CCDC25 and KLHL41 were identified as potential biomarkers for steatosis, GP1BA as a candidate marker for MASH and C7, IGHD and GNB1 as potential biomarkers for fibrosis severity." (PMID 41301514, 2025).
triple-negative breast carcinoma (1 paper, 2020). An invasive breast carcinoma which is negative for expression of estrogen receptor (ER), progesterone receptor (PR), and human epidermal growth factor receptor 2 (HER2). "IGHD gene served as suppressor genes in the recurrence of triple-negative breast cancer." (PMID 33072067, 2020).
uveitis (1 paper, 2020). An inflammatory process affecting a part of or the entire uvea. "Overall, distinct clusters of uveitis cases (termed “JIA uveitis 2”) became apparent, characterized by distinct expression of IGHD, CCR7, IGHM and CD27." (PMID 33042130, 2020).
virus infection (1 paper, 2013). "Regarding the IgD, complete IGHD transcripts were expressed at very low level in the trout spleen, even after virus infection." (PMID 23326228, 2013).
tumor (10 papers, 2019 to 2024). "Although LAG-3 B cells comprised a minor portion of total tumor-infiltrating B cells (49 cells), evaluating other cellular markers, we observed co-expression of IGHD and PDCD1 alongside LAG-3." (PMID 38773133, 2024). "The expression level of IGHD, which is major marker of NBCs, and the proportion of IGHD‐positive cells was the lowest in tumour cells with NACT among the three tissue source types." (PMID 36650114, 2023). "Besides, IGHD has also been studied in BC, being a protective factor for BC recurrence and functioning as tumor suppressor." (PMID 36581948, 2022). "Our further research suggested that WAKMAR2 is crucial in regulating the tumour microenvironment and may function by regulating immune-related genes, including IL27RA, RAC2, FABP7, IGLV1-51, IGHA1, and IGHD." (PMID 34321580, 2021). "Since the presence of tumor-infiltrating B cells was usually correlated to better overall survival and treatment outcomes, we selected several representative B-cell signatures (CD79A, MS4A1, IGHD, and FCRL4) and examined their prognostic values in NPC patients." (PMID 33750785, 2021).
cancer (2 papers, 2019 to 2022). A tumor composed of atypical neoplastic, often pleomorphic cells that invade other tissues. "There have been no reports on IGHD and IGHE expression in cancer cells; our results showed that both IGHD and IGHE were expressed, though rarely, in myeloblasts." (PMID 35205028, 2022).
infection (2 papers, 2022 to 2025). The state of being infected such as from the introduction of a foreign agent such as serum, vaccine, antigenic substance or organism. "Overall, we speculate that the differences in IGHV, IGHD, and IGHJ gene usage between Bartha-K61 strain infection group and XJ strain infection group may be associated with strain variation and specific antigenic stimulation." (PMID 35715782, 2022). "The BCR repertoire responding to different infections or vaccinations has generally preference for specific IGHV, IGHD or IGHJ genes." (PMID 35715782, 2022). "To assess the molecular diversity of BCR H-CDR3 repertoire after different PRV strains infection, we have detected usage of IGHV, IGHD, and IGHJ genes and also, CDR3 sequences of BCR of mice spleen following inoculation with PRV vaccine strain (Bartha-K61), and variant strain (XJ)." (PMID 35715782, 2022). "Here, to assess the molecular diversity of BCR H-CDR3 repertoire after different PRV strains infection, we detected the IGHV, IGHD, IGHJ genes usage and CDR3 sequence changes of mice spleen with PRV vaccine strain (Bartha-K61), variant strain (XJ) and mock infection by high-throughput sequencing." (PMID 35715782, 2022).
IGHD also shares sentences with these, for which no sentence is quoted: melanoma (2 papers); colitis (1); diabetes (1); invasive breast carcinoma (1); Mendelian diseases (1); psoriasis (1); rheumatic disease (1).